KCNQ1DN (KCNQ1 downstream neighbor)
Synonyms: BWRT; HSA404617
Gene: Long non-coding RNA gene on chromosome 11 (2,870,033 to 2,872,105, forward strand). Ensembl gene ENSG00000237941.
Diseases named in the same sentence as KCNQ1DN in open-access papers:
KCNQ1DN is named in the same sentence as 6 diseases in open-access papers, as found by Europe PMC text mining. Sharing a sentence is not in itself a finding about the gene and the disease. The quoted sentences say what the papers report.
Wilms tumor (4 papers, 2017 to 2022). An embryonal neoplasm characterized by the presence of epithelial, mesenchymal, and blastema components. "KCNQ1DN, which imprinted and mapped between CDKN1C and KCNQ1 on chromosome 11p15.5, is usually associated with Wilms' tumor." (PMID 33835050, 2021). "In addition, the ARACNE analysis inferred an interaction between CDC45 and KCNQ1DN (SF 6), an lncRNA related to Wilms’ tumor or nephroblastoma, the most common pediatric renal cancer affecting children 3–5 years old." (PMID 35445848, 2022). "In Wilms’ tumors, reduced expression of lncRNA KCNQ1DN existing far from the H19/IGF2 region and may play regulatory role in tumor progression." (PMID 31001325, 2019).
renal cell carcinoma (3 papers, 2019 to 2023). "KCNQ1DN's DNA methylation is associated with aging and its lncRNA was found downregulated in renal cell carcinoma in a in vitro study." (PMID 36400229, 2023). "Furthermore, it has recently been found that KCNQ1DN is notably decreased in renal cell carcinoma (RCC) tissues and cell lines." (PMID 35445848, 2022).
breast tumors (1 paper, 2016). "We also found that two lncRNAs, CAHM and KCNQ1DN, are down-regulated in breast tumors compared to healthy normal controls in our study." (PMID 27597120, 2016).
tumor (3 papers, 2019 to 2025). "The in vivo studies in nude mice showed that overexpression of KCNQ1DN significantly repressed xenograft tumor growth and c-Myc expression." (PMID 31528231, 2019). "Quantitative methylation analysis was further performed on KCNQ1DN gene promoter (-1111/-565) with an amplicon covering 22 CpG sites in non-tumor and RCC tissues." (PMID 31528231, 2019). "Taken together, the tumor-bearing studies in nude mice indicated that overexpression of KCNQ1DN inhibits the growth of xenograft RCC and the expression of c-Myc in vivo." (PMID 31528231, 2019). "lncRNAs such as DIO3OS, EMX2OS, KCNQ1DN, KCNQ1OT1, LOH12CR2, and RFPL1S have been shown to associate with a negative gene signature, which links lncRNA to tumor suppression mechanisms." (PMID 41300873, 2025).
KCNQ1DN also shares sentences with these, for which no sentence is quoted: cancer of the kidneys (1 paper); renal carcinoma (1).